RMP24 (ribonuclease MRP subunit p24)
Description:
Specific component of the MRP ribonucleoprotein endoribonuclease, Rnase/Mrp complex, a ribonucleoprotein complex involved in pre-rRNA processing.
Synonyms: C18orf21; XTP13; PNAS-124; PNAS-131; HsT3108
Tractability: Antibody: the Human Protein Atlas places it where antibodies can reach. PROTAC: ubiquitination databases record sites on it; its protein half-life has been measured.
Gene: Protein-coding gene on chromosome 18 (35,972,625 to 35,979,286, forward strand). Ensembl gene ENSG00000141428.
Subcellular location: Nucleus
Subcellular location (Human Protein Atlas): Nucleoli; Plasma membrane
Gene Ontology:
Biological process: RNA processing
Cellular component: nucleus; ribonuclease MRP complex
Genetic constraint (gnomAD): Loss-of-function variants: 20 observed, 25.27 expected, observed/expected ratio (o/e) 0.79, 90% interval 0.56 to 1.15. The upper end of that interval is the gene's LOEUF score, 1.15, which puts it in group 5 of 6, group 1 being the genes least tolerant of losing a copy. Missense variants: 265 observed, 271.86 expected, observed/expected ratio (o/e) 0.97, 90% interval 0.88 to 1.08. Synonymous variants: 102 observed, 99.75 expected, observed/expected ratio (o/e) 1.02, 90% interval 0.87 to 1.21.
Homologues: Orthologues: chimpanzee C18H18orf21 (98% identical), macaque C18H18orf21 (87% identical), pig C18orf21 (83% identical), dog C7H18orf21 (82% identical), guinea pig C18orf21 (78% identical), rabbit C18orf21 (78% identical), mouse 2700062C07Rik (73% identical), rat C18h18orf21 (71% identical), tropical clawed frog c6h18orf21 (40% identical), zebrafish si:dkey-184p18.2 (30% identical).
Diseases named in the same sentence as RMP24 in open-access papers:
RMP24 is named in the same sentence as 1 disease in open-access papers, as found by Europe PMC text mining. Sharing a sentence is not in itself a finding about the gene and the disease.
RMP24 shares sentences with these, for which no sentence is quoted: cancer (1 paper).